PAK4 (p21 (RAC1) activated kinase 4)
Diseases named in the same sentence as PAK4 in open-access papers (continued):
Sharing a sentence is not in itself a finding about the gene and the disease.
tumor (continued). "Early studies suggest that PAK4-targeting PROTACs not only inhibit tumor growth but also enhance immune responses, potentially improving outcomes when combined with existing therapies like immune checkpoint inhibitors." (PMID 39199615, 2024). "In the present study, the PAK4 inhibitor abrogated the expression of β-catenin and PD-L1 in tumour cells of the OSCC tumour-bearing mice." (PMID 38890401, 2024). "In both the nude mice and C57BL/6J mice, the overexpression of PAK4 significantly increased tumor growth, and tumor growth was significantly decreased with the knockdown of PAK4." (PMID 39273017, 2024). "In our study, we also investigated the relation of Pak4 with tumor infiltration level and T cell exhaustion using TIMER database." (PMID 38807162, 2024). "In contrast, in vivo tumor growth and pulmonary metastasis were significantly decreased with the knockdown of PAK4." (PMID 39273017, 2024). "The expression of PD-L1 was found to be significantly lower on tumour cells of PAK4 inhibitor-treated mice than in control mice." (PMID 38890401, 2024). "We knocked down PAK4 in the RAC1‐overexpressing OC cell lines ES‐2 and A2780 and found that PAK4 knockdown reversed the tumor‐promoting effects of RAC1 overexpression." (PMID 39224538, 2024). "We compared the surface phenotypes of tumour-infiltrating CD11c+CD103+ DCs between PAK4 inhibitor-treated and control mice." (PMID 38890401, 2024). "Collectively, these findings suggest elevated gene repair and cell proliferation functions in high PAK4 patients, potentially contributing to tumor cell survival and replication." (PMID 38424218, 2024). "Taken together, our results revealed that the targeting PAK4 in OSCC exerts not only the direct anti-tumour effect such as suppressing tumour cell proliferation but also enhancement of anti-tumour immune responses by activating T cell immune responses." (PMID 38890401, 2024). "The expression of β-catenin was significantly lower in tumour cells of PAK4 inhibitor-treated mice than that that in control mice." (PMID 38890401, 2024). "The proportion of IFN-γ-producing T-cells among CD8+ T-cells was significantly increased in the tumours of PAK4 inhibitor-treated mice compared with that in control mice." (PMID 38890401, 2024). "To evaluate the function of DCs, we compared the stimulatory functions of CD11c+CD103+ DCs and CD11c+CD103− DCs from the tumours of PAK4 inhibitor-treated mice by co-cultivation with splenic T-cells from naive mice in vitro." (PMID 38890401, 2024). "Secondly, only extrahepatic and intrahepatic tumor transplantation models were used in this study to investigate the role of PAK4 in regulating ketogenesis and its impact on tumor growth." (PMID 37591884, 2023). "PAK4 was overexpressed in metastatic tumor tissues compared with primary tumor and normal tissues, and PAK4 expression was correlated with worse survival of HCC patients." (PMID 36672500, 2023). "The results of this study show that using these exosomes in vivo (intratumor injection) and in vitro leads to a decrease in PAK4 expression, a reduction in tumor growth, and an increase in the survival of mouse models." (PMID 37287924, 2023). "PAK4 plays a critical role in coordinating the abnormal development of blood vessels and the exacerbation of low-oxygen (hypoxic) conditions within a tumour." (PMID 38067120, 2023). "PAK4 knockout recovered the expression of adhesion proteins in tumour-derived endothelial cells, leading to normalisation of vasculature, which was associated with increased T cell infiltration and decreased tumour growth." (PMID 38067120, 2023). "CD31, a primary blood vessel marker, was increased in tumours treated with anti-PD-1 in PAK4 KO mice." (PMID 38067120, 2023).
tumor (continued). "In an orthotopic tumor model, Hepa1-6 cells were directly injected into the livers of WT and Pak4 LKO mice." (PMID 37591884, 2023). "PAK4, CPNE1, and MCT4 are predicted to each have miR-330-5p binding sites and are tightly linked to tumor metabolism or glycolysis." (PMID 37532687, 2023). "A combination of anti-PD-1 treatment and a PAK4 inhibitor enhanced anti-tumour responses compared to anti-PD-1 treatment alone." (PMID 38067120, 2023). "Resistance to PD-1 blockade was overcome after genetic deletion of PAK4, and the combination of anti-PD-1 with PAK4 inhibition improved anti-tumor response versus PD-1 blockade alone." (PMID 37345111, 2023). "Thirdly, NCoR1 was highly phosphorylated in tumor tissues, in line with the enhanced PAK4 protein levels." (PMID 37591884, 2023). "The structural normalisation of blood vessels through PAK4 inhibition can enhance drug distribution and mitigate intra-tumoral hypoxia, ultimately resulting in enhanced tumour responses to molecular targeted therapy as well as radiotherapy and chemotherapy." (PMID 38067120, 2023). "p-Bad-microRNA axis regulates drug resistance in pancreatic ductal adenocarcinoma (PDAC), and blocking of PAK4 induces reduction of Bad phosphorylation and upregulation of tumor-suppressive miRNAs in PDAC." (PMID 36105226, 2022). "Most human tumors, except LGG, had significantly higher tumor purity in the PAK4 high expression group than in the PAK4 low expression group (p < 0.001), while the stromal, immune, and ESTIMATE scores show the opposite trend." (PMID 36064705, 2022). "In the PAK4 knockout (KO) B16 cell, β-catenin phosphorylation was decreased and treatment with PD-1 blockade significantly reduced tumor growth." (PMID 36105226, 2022). "PAK4 is also minimally expressed in normal tissues, while it is overexpressed in various tumors and thus regarded as a tumor marker and treatment target." (PMID 35800076, 2022). "As a popular tumor biomarker, PAK4 plays a vital role in the prognosis of patients with various tumors in the digestive system, reproductive system, and respiratory system." (PMID 35800076, 2022). "Accordingly, in glioblastoma, the inhibition of PAK4 can repair the microenvironment of abnormal tumor blood vessels and increase the efficacy of CAR-T." (PMID 35800076, 2022). "In the process of tumor cell proliferation, PAK4 shows positive significance in regulating cell mitosis and controlling the cell cycle." (PMID 35800076, 2022). "Activated PAK4 promotes the proliferation, migration, invasion, and treatment resistance of tumor cells through the activation of various signaling pathways." (PMID 35800076, 2022). "In contrast, Pak4 knockdown induces the cell rounding attributed to the actin depolymerization in tumor cell lines H1229 and HCT116 cells, suggesting that the control of the fine morphology of cells requires strict regulation of Pak4 activity." (PMID 36301793, 2022). "At the moment, PAK4 has been studied extensively in relation to tumor biology function, but there is still conflicting information regarding its role in cell aging." (PMID 35800076, 2022). "Although PAK4 can only phosphorylate β-Catenin, it has been reported that PAK4 can activate AKT or MEK/ERK in various tumor processes." (PMID 36230657, 2022). "PF-3758309 is an orally available, potent and reversible PAK4 ATP-competitive inhibitor, which has been reported that it can inhibit tumor cell anchorage-independent growth, induce tumor cell apoptosis, and inhibit tumor cell proliferation." (PMID 35401439, 2022). "To summarize, PAK4 plays an important role in tumor occurrence and development and is important in prognosis and as a tumor biomarker." (PMID 35800076, 2022). "PAK4, as a selective regulator of genetic reprogramming and abnormal tumor blood vessels, plays a vital role in tumor resistance to CAR-T." (PMID 35800076, 2022). "Similar to the effect of Inka2 on tumor metastasis, Pak4 inhibitor PF-3758309 blocks the growth of multiple tumor xenografts." (PMID 36301793, 2022).
tumor (continued). "This article summarizes the role of PAK4 in tumor cytogenesis, proliferation, survival, migration invasion, and drug resistance." (PMID 35800076, 2022). "Previous studies have shown that the abnormal expression of the PAK4 gene promotes aggressive and invasive metastasis of tumor cells, and targeted therapies against PAK4 can treat several malignancies." (PMID 36408417, 2022). "The observation that PAK4 KO tumors require the addition of anti-PD-1 to decrease tumor growth, highlights the importance of overcoming adaptive immune resistance mechanisms and blocking the PD-1/PD-L1 interaction." (PMID 36588582, 2022). "As a potential tumor biomarker, PAK4 has great clinical and pathological significance in the evaluation of prognostic and pathological indicators." (PMID 35800076, 2022). "It has been shown that p21-activated kinase 4 (PAK4) inhibition normalizes the tumor vascular microenvironment and makes GBM more sensitive to CAR-T cell therapy." (PMID 36261831, 2022). "This overview should be of assistance for future research on PAK4 and tumors and provide new ideas for tumor treatment and prognostic evaluation of patients." (PMID 35800076, 2022). "Taken together, AFAP1-AS1/LINC01419-miR-143-5p-PAK4/CNN2 represents a potential tumor-promoting up-down-up axis." (PMID 35629368, 2022). "The effect of Nuplazid on the PAK4 signaling pathway in tumour tissues was examined, and the results indicated that the Nuplazid treatment strongly suppressed the phosphorylation of MAPK1 in LEG110 tumours." (PMID 34912075, 2022). "Although PAK4 is related to tumor size, stage, and severity, it is overexpressed in various tumors with poor specificity." (PMID 35800076, 2022). "A large number of literature references have shown that PAK2 and PAK4 are directly involved in the regulation of tumor invasiveness and metastasis by influencing their client protein behaviors." (PMID 34437425, 2021). "Residual tumor analysis confirmed a reduction in total and phosphorylated PAK4 and activation of the pro-apoptotic cascade." (PMID 35008323, 2021). "Studies show PAK4 overexpression in tumor cell lines of the ovary, pancreas, colon, prostate, lung, and leukemia compared to their respective normal cell lines." (PMID 35008323, 2021). "In summary, we have demonstrated potent anti-tumor activity of a PAK4-NAMPT dual inhibitor, KPT-9274, in preclinical models of NHL." (PMID 35008323, 2021). "In vivo studies were performed to assess the effect of PAK4-NAMPT inhibition on NHL tumor xenografts." (PMID 35008323, 2021). "Taken together, this in vivo data supports the findings of the in vitro studies in ES cell lines – PAK4 is involved in ES tumor-promoting processes, and its inhibition suppresses tumorigenesis." (PMID 36594908, 2021). "Particularly, PAK1 and PAK4 are often upregulated in human tumors, and the tumor cells with upregulated PAK1 and PAK4 tend to become dependent on PAK signaling." (PMID 34471161, 2021). "Our recent kinome-wide genetic screening of mesenchymal-like transcriptional activation in tumor ECs identifies PAK4 as an innovative target to reprogram ECs in glioblastoma." (PMID 34987525, 2021). "Genetic ablation or pharmacological inhibition of PAK4 showed an increase in expression of adhesion molecules in tumor ECs, a decrease in vessel abnormalities with improved T-cell infiltration, rendering tumors more sensitive to CAR T immunotherapy." (PMID 34987525, 2021). "Tumor analysis revealed a decrease in PAK4 expression, as well as its downstream effector β-catenin." (PMID 35008323, 2021). "Contrary to the serum profile, urine from OH-BBN induced C57BL/6 mice displayed increased levels of the pro-inflammatory cytokines Ccl3 and Il1β, as well as an upregulation of tumor promoting Ppp1r2, Pak4, tumor growth marker Nadk, and Dctn2." (PMID 34232958, 2021). "They packaged the PAK4-siRNA in exosomes for delivery to tumor cells in vitro and in vivo and showed reduced tumor growth and enhanced survival in mice." (PMID 33374908, 2020).
tumor (continued). "Here, we find that the nuclear PAK4 promotes osteoclastogenesis and tumor-induced osteolysis via phosphorylating RUNX1." (PMID 32549768, 2020). "Both XPO1 and PAK4 inhibitors, when combined with lenvatinib, showed superior anti-tumor activity in 8505C sub-cutaneous xenograft." (PMID 31905765, 2019). "In PAK4 group, among 15 cases, 13 showed diffuse staining within tumor cells; the staining intensity was 1 in six cases and 2 in nine cases, respectively." (PMID 31795447, 2019). "Strikingly, the effects of PAK4 gene depletion on tumor formation were even more prominent in the male PyMT." (PMID 31399573, 2019). "In our analysis of human tumor samples, we saw elevation of PAK4 in all four patient tumor samples compared to matched benign esophageal epithelial controls as assessed by copy number." (PMID 29983868, 2018). "MiR-199a/b-3p can target tumor-promoting PAK4 to suppress HCC growth through inhibiting PAK4/Raf/MEK/ERK pathway." (PMID 29951542, 2018). "Other targets of miR-199a include the tumor-promoting p21 (RAC1) activated kinase 4 (PAK4), the mammalian target of rapamycin (mTOR) and c-Met, which have been described as tumor suppressors in the context of HCC." (PMID 29337905, 2018). "More importantly, increased levels and activity of PAK4 were found to significantly correlate with tumor size and tumor TNM stage." (PMID 28178642, 2017). "Levels of PAK4 and PAK4 phosphorylated at serine 474 correlated significantly with tumor size and TNM stage." (PMID 28178642, 2017). "Many studies have demonstrated the roles of PAK4 in regulating tumor cell mobility, invasion, and proliferation." (PMID 28680855, 2017). "The growth of tumor cells in mice injected with PAK4-expressing cells faster than control animals at different time points." (PMID 28407679, 2017). "Overexpressed miR-145 exerts its anti-tumor function by modulating a target gene, PAK4, which blocks the activation of AKT and ERK1/2 pathways, thus inhibiting tumor growth." (PMID 28061475, 2017). "The results showed that 90.8% of tumor samples and 9.2% of normal thyroid tissue samples showed positive PAK4 staining, while 82.7% of tumor samples and 15.3% of normal thyroid tissue samples were positive for p-PAK4." (PMID 28178642, 2017). "Further analysis revealed that the upregulation of PAK4 and p-PAK4 in PTC samples was significantly associated with tumor size (all P < 0.01) and tumor TNM stage (all P < 0.01)." (PMID 28178642, 2017). "P54 protein has a certain relationship with tumor, and P54 provides a new basis for the further improvement of PAK4 tumor signaling pathway." (PMID 27297086, 2016). "And the PAK4 expression in mRNA level in the peritumor tissue (more than 2 cm from tumor tissue) and in tumor tissue in each patient was examined with RT-qPCR method." (PMID 26411419, 2015). "The NSCLC tissues had significantly higher PAK4 staining scores than the adjacent non-tumor tissues (p < 0.01)." (PMID 25975262, 2015). "Data demonstrate that ~96.4 % of the total tumor samples have an intense staining of PAK4, which is predominantly localized in the cytoplasm with some diffuse staining in the nucleus." (PMID 25238288, 2014). "An overexpression of PAK4 has also been observed in tumor tissues and cell lines of various origins." (PMID 25238288, 2014). "PAK4 has been confirmed to be correlated with the development and progression of various tumour cells." (PMID 27919028, 2014). "In the group of PAK4-positive tumor specimens, 25 (44.6 %) were weakly stained, 19 (33.9 %) were moderately stained and the remaining 10 (17.9 %) tumor specimens were strongly stained." (PMID 25238288, 2014). "An important difference between the Pak1 and Pak4 studies is that, in contrast to Pak1, even wild-type Pak4 leads to transformation of mammary epithelial cells and tumorigenesis in mice, and it leads to tumor formation at a high frequency." (PMID 23326684, 2012).
tumor (continued). "In fact, an inhibitor that blocks the kinase activity of Pak4 and other Pak family members (PF-3758309) has growth inhibitory activity towards a large number of tumor cell lines, and a newer Pak4 inhibitor, LCH-7749944, has also been reported recently." (PMID 23326684, 2012). "Group II PAKs (PAK4–6) regulate a wide variety of cellular functions, and PAK deregulation has been linked to tumor development." (PMID 17292838, 2007). "Interestingly, despite this higher angiogenesis in PAK4KO tumours, the VEGFA expression in PAK4KO tumour cells was reduced compared to the WT, suggesting the primary role of fibronectin in promoting angiogenesis by the PAK4 knockout." (PMID 41294859, 2025). "However, the mechanism involved is not well understood, although previous studies have suggested that the inhibition of PAK4 reprograms the tumor vasculature to promote the infiltration of T cells." (PMID 39941877, 2025). "Knockout of PAK1 or PAK4 enhanced tumour vasculature normalisation by increasing pericyte coverage." (PMID 40943273, 2025). "By uncovering significant changes in gene expression and protein remodeling, including the upregulation of PAK4 and alterations in actin dynamics, this research sheds light on the mechanisms driving tumor cell migration and epithelial-mesenchymal transition (EMT)." (PMID 40301999, 2025). "The downregulation of these markers suggests that knockout of PAK1 and/or PAK4 may suppress VM formation, thereby contributing to vascular normalisation and altered tumour vascular architecture observed in our models." (PMID 41228228, 2025). "The established roles of PAK1 and PAK4 in regulating intra-tumoral T-cell responses suggest that these kinases may also influence the tumour vasculature." (PMID 40943273, 2025). "The pivotal role of PAK4 in activating mesenchymal-like transcription within tumor endothelial cells may induce the formation of abnormal vasculature in tumors." (PMID 40332759, 2025). "Tumour‐derived PAK4 phosphorylates VE‐cadherin, disrupting EC junctions, increasing vascular permeability and promoting TC extravasation, a process notably observed in aggressive tumours such as glioblastoma." (PMID 40268524, 2025). "Inhibiting PAK4 can normalize the tumor vascular microenvironment." (PMID 40332759, 2025). "These complementary mechanisms suggest that combined PAK1 and PAK4 inhibition could enhance therapeutic efficacy through both vascular and tumour-intrinsic mechanisms." (PMID 41228228, 2025). "Additionally, depletion of PAK4 can increase tumor-specific T cell infiltration, rendering tumors sensitive to PD-1 blockade therapy." (PMID 40332759, 2025). "The inhibition of PAK4 suppresses PDA by stimulating the tumor infiltration of cytotoxic T cells." (PMID 39941877, 2025). "By combining PAK4 inhibition with CAR-T cells engineered to target the EGFR variant III, researchers successfully reprogrammed the vasculature, facilitating immune cell adhesion and improving the penetration of T cells into the tumor." (PMID 40173050, 2025). "Moreover, silencing PAK4 enhances vascular genesis and increases endothelial cell adhesion molecules within the tumor microenvironment, facilitating recruitment of CD8 lymphocytes." (PMID 40332759, 2025). "In addition to genetic knockout models, several small-molecule PAK inhibitors—including PF-3758309, FRAX597, and the dual PAK4–NAMPT inhibitor KPT-9274—have shown potent anti-tumour activity in preclinical studies." (PMID 41228228, 2025). "Our results suggest that PAK4 inhibition in OSCC can have direct anti-tumour and immunomodulatory effects, which might benefit the treatment of this malignancy." (PMID 38890401, 2024). "Furthermore, the immunohistochemical staining intensity of PAK4 in OSCC cases was found to be positively correlated with tumour size." (PMID 38890401, 2024). "However, nothing is known about the anti-tumour and immunomodulatory effects of PAK4 inhibition in OSCC." (PMID 38890401, 2024).